DNMT1 (DNA methyltransferase 1)
Diseases named in the same sentence as DNMT1 in open-access papers (continued):
Sharing a sentence is not in itself a finding about the gene and the disease.
cancer (continued). "Therefore, DNMT1 has been identified as a therapeutic target for the treatment of some cancers." (PMID 37510229, 2023). "Moreover, genistein attributed its anti‐cancer activity in BC cells by demethylating and reactivating methylation‐silenced tumor suppressor genes via direct contact with inhibition of both DNA methyltransferase 1 (DNMT1) catalytic domain activation and DNMT1 expression." (PMID 37132286, 2023). "Moreover, several studies have confirmed that lncRNA Neat1 could sponge miR-185-5p to regulate IGF2 expression or DNMT1/mTOR signaling, promoting cancer progression." (PMID 35501920, 2022). "As Dnmt1 is known to interact with various proteins and thus may possess DNA-methylation-independent functions, additional Dnmt1-independent models would be valuable for further defining and investigating the diverse roles of DNA hypomethylation in cancers." (PMID 33947834, 2021). "Moreover, downregulation of DNMT1 could suppress cancer cell viability, migration and invasion through upregulation of KLF4 expression." (PMID 33596966, 2021). "Moreover, the expression of PPARγ and DNMT1 was found to be dysregulated in various cancers." (PMID 34439147, 2021). "TQ shows promising inhibitory effects on several cancers through its targeting of several mechanisms, including the upregulation of TSGs, and it shows only mild cytotoxic effects on matched normal cells, making it a promising hypomethylating agent through its specific inhibition of DNMT1." (PMID 33922029, 2021). "Moreover, zebularine can suppress the interaction of DNMT1 with G9a histone methyltransferases, which may regulate the survival and apoptosis of human cancer cells." (PMID 34452630, 2021). "LSD1 (protein lysine-specific histone demethylase 1A), also named KDM1A, demethylates a range of important cancer-causing nonhistone proteins, including DNMT1, HSP90 and STAT3, and could be a promising target." (PMID 32708698, 2020). "Interestingly, miR-34a might be regulated by DNMT1 through promoter methylation in cancer cells or CSLCs." (PMID 32308683, 2020). "In addition to serving as the starting point in future drug development efforts, a compound targeted at DNMT1 enzymatic activity could be useful in furthering our understanding of cancer etiology." (PMID 31306451, 2019). "However, causative data and mechanistic insights into these processes are limited: deletion of DNA methyltransferase 1 (DNMT1), the enzyme that maintains DNA methylation during cell division, is lethal in all dividing somatic mouse cells as well as human cancer cells." (PMID 31320637, 2019). "However, it was unexpected that hypermethylated genes would continue to be repressed after UHRF1 depletion, as it is well documented that UHRF1 acts as a hub to recruit multiple proteins, including DNMT1, HDAC1, G9a, and EZH2, to repress cancer-associated genes in cancer cells." (PMID 31064417, 2019). "Furthermore, we surmised whether downregulation of UHRF1/DNMT1 by 2i could be explored for targeting aberrant DNA methylation in cancer cells." (PMID 30696879, 2019). "However, some else reports demonstrated that low DNMT1 contributed to the stemness of cancer stem cell-like cells and treatment with 5 Aza in HCC cells could increase the number of cancer stem cell-like cells." (PMID 30064482, 2018). "Thus, DNMT1 has emerged as an attractive target for cancer chemotherapy." (PMID 29783680, 2018). "Numerous post-translational modifications of DNMT1 could modulate its activity in cancers." (PMID 29449903, 2018).
cancer (continued). "Given the prior observations that upregulation of DNMT1-mediated gene silencing can promote tumor cell migration and metastasis in several types of cancers, we speculate that DNMT1 induction, at the least partially, is responsible for the phenotype of cancer cells with reduced DBCCR1 expression." (PMID 28427182, 2017). "It is well known that the dietary phytochemicals (e.g., curcumin, lycopene, genistein) reverse abnormal DNA methylation landscape in various types of cancer, but it is unknown whether TQ, another phytochemical compound, possesses inhibitory activity on DNMT1-dependent DNA methylation." (PMID 28415607, 2017). "Thus, NKX6.3 inactivation in gastric mucosa may increase activity of NF-kB and DNMT1 and reduce Hace1 expression, subsequently progressing to atrophy, intestinal metaplasisa and cancer." (PMID 28584243, 2017). "Thus, inhibition of DNMT1 could be a promising therapeutic potential for treating cancers including NPC." (PMID 28360411, 2017). "However, in cancer cells, IL-6 induces DNMT1 to inhibit miR-370 expression." (PMID 27499248, 2016). "The high expression of DNMT1 was demonstrated to play a key role in cell transformation in vitro, suggesting that the abnormal expression of DNMT1 may have influence to the development of human cancer." (PMID 27777512, 2016). "Therefore, DNMT1 inhibition is an important potential approach for cancer treatment." (PMID 27525019, 2016). "Interestingly a recent report showed that, although 5-azacytidine (5-AZA) reduced DNMT1 expression levels in PC3 and DU145 cells, this result was associated with EMT and cancer stem cell (CSC) phenotypes, events likely to be counterproductive when treating PCa." (PMID 28042859, 2016). "This may be critical when considering the use of DNMT1 inhibitors in anti-cancer therapies." (PMID 26504497, 2015). "Thus, inhibition of DNMT1 may represent a promising approach for the prevention and treatment of many cancers 10–13." (PMID 25598321, 2015). "The distinct roles of DNMT1 maintenance-dependent and -independent methylation activities may explain the inefficiency of DNMT1 inhibitor drugs in the treatment of cancers, because only DNMT1-dependent patterns are reduced and DNMT1-independent patterns are not." (PMID 26032981, 2015). "As a partial cooperation between de novo and maintaining Dnmts have also been reported increasing methyl donors accessibility may palliate mMase defects in cancers mainly promoted by Dnmt1/PCNA/URHF1 disruption and limit further chromosomal instability and local hypomethylations." (PMID 24709797, 2013). "This is consistent with the recent observation that hypomethylation in gastric CAFs could not be attributed to any difference in mRNA levels of DNMT1, DNMT3a, or DNMT3b between normal and cancer-associated myofibroblasts." (PMID 22984426, 2012). "The observed resistance to demethylation at these loci could be explained by redundant activities in the establishment and maintenance of DNA methylation by DNMT3A and DNMT1, respectively, being capable of activity compensating for the loss of DNMT3B in human cancer cells in vitro." (PMID 22563479, 2012).
cancer (continued). "This suggests that a therapeutically-induced inhibition of UHRF1 activity or expression could prevent the action of its preferred partners, HDAC1 and DNMT1, leading to a re-expression of the tumour suppressor genes p16INK4A and thus allowing the cancer cells to undergo apoptosis." (PMID 21496237, 2011). "Having demonstrated the ability of Snail to bind and recruit histone deacetylase 1 and DNA methyltransferase 1 in this context, we set out to look for other interactions that could affect its ability to promote oncogenic transformation and cancer cell invasion." (PMID 22128911, 2011). "Human cancer cells may differ in their threshold requirement for DNMT1." (PMID 21629434, 2010). "Taking into account the low intrinsic de novo methyltransferase ability of DNMT1 cases, this protein may also be capable of initiating aberrant CpG island methylation patterns, replacing the conventional de novo DNMT3s, at least in cancer cells." (PMID 21629434, 2010). "To determine whether the disruption of the Dnmt1/PCNA/UHRF1 interactions can promote the tumor transformation of Astro#40 and Ntv-a cells, we firstly investigated whether these cells acquired some hallmark of cancer after their transfection by the pUP plasmid." (PMID 20613874, 2010). "A Dnmt1-deficient cancer cell line showed little loss of DNA methylation, suggesting that the de novo methyltransferases can maintain a high level of DNA methylation in the absence of Dnmt1 in neoplastic cells." (PMID 15799776, 2005). "In the process of cancer development, various DNMTs (DNMT1, DNMT3A, and DNMT3B) and HDACs (HDAC 1, 2, 3, and 6) are reported to be overexpressed in different cancers." (PMID 41562705, 2026). "In laboratory settings, DNC has been shown to reactivate the expression of miR-34s by inhibiting DNMT1, DNMT3A, and DNMT3B in HepG2 and Huh7 cell lines, reducing the viability of these cancer cells." (PMID 39829957, 2025). "In line with this study, kaempferol was found to reduce DNMT1, DNMT3B and HDAC activity in different cancers." (PMID 40159638, 2025). "Specifically, STAT3 phosphorylation has been found to increase DNMT1, DNMT3A, and DNMT3B expression in cancer cells." (PMID 40427627, 2025). "DNMTs (DNMT1, DNMT3A and DNMT3B) upregulation is promoted by oncoproteins E6 and E7 and the magnitude of their expression is directly related to cancer progression in CC." (PMID 40159638, 2025). "For instance, DNMT1’s role in the epithelial-mesenchymal transition (EMT) and cancer stem cell (CSC) phenotypes highlights its significant impact on tumor initiation and progression." (PMID 40034825, 2025). "The results indicated that USP37 was significantly associated with at least one of the four methyltransferase genes (DNMT1, DNMT2, DNMT3A, and DNMT3B) in various cancer types, except UCS." (PMID 40926837, 2025). "Although cancer genomes often exhibit global hypomethylation, this occurs, paradoxically, alongside the frequent upregulation of DNA methyltransferase 1 (DNMT1) and its cofactor, UHRF1, in many cancers." (PMID 40558829, 2025). "The study highlights a multi-target mechanism, with strong interactions observed against key protein targets in cancer pathways, including HDM2, DNMT1, AKT2, and PARP-1." (PMID 40575462, 2025). "Mechanistically, NF-κB activation enhances histone acetylation at promoters of inflammatory cytokines (IL-8, COX-2), while STAT3 can recruit DNMT1 to hypermethylate SOCS gene promoters, reinforcing a self-sustaining inflammatory state in cancer." (PMID 41226277, 2025). "DNMT1's role in maintaining DNA methylation patterns is critical for the epigenetic regulation of gene expression, suggesting that its upregulation could support aberrant cancer cell proliferation by silencing tumor suppressor genes and activating oncogenic pathways." (PMID 40090465, 2025).
cancer (continued). "Upon treatment of the different cancer cell lines (HaCaT, HepG2, and A549 cells) with TRZ in our study, DNMT1, DNMT3a, and DNMT3b were significantly upregulated at concentrations of 20, 40, and 80 μM for a duration of 24 h." (PMID 40077783, 2025). "Molecular docking and Prime MM-GBSA screening of seventeen cancer-related protein targets, including Human Double Minute 2 protein (HDM2), DNA methyltransferase-1 (DNMT1), Protein Kinase B (AKT2), and Poly (ADP-ribose) polymerase 1 (PARP-1), were conducted." (PMID 40575462, 2025). "DNA methyltransferase 1 (DNMT1) is a key enzyme responsible for maintaining DNA methylation patterns and has been shown to play a pivotal role in cancer epigenetics." (PMID 41381440, 2025). "DNMT3a expression was the highest in VLSIL (VIN I) samples, while DNMT1 was only expressed in VHSIL (VIN III) and carcinoma samples." (PMID 40022051, 2025). "DNA Methyltransferase 1 (DNMT1), a member of the DNA methyltransferase family, is highly expressed in various cancers." (PMID 38778379, 2024). "EZH2 was also shown to interact with DNMT1, DNMT3A, and DNMT3B in cancer cells and to result in the hypermethylation of genes, leading to increased permanent silencing of target genes." (PMID 39409007, 2024). "For DNA methylation regulatory factors, the specific functions and molecular mechanisms of DNMT1, DNMT3A, DNMT3B, and TET family proteins have been extensively studied in various malignant tumors." (PMID 38308276, 2024). "To investigate the respective roles of DNMT1 and UHRF1 in cancer cells, we chose as a model the human colorectal cell lines HCT116 and DLD1, as they have been widely used to study the genetic and epigenetic events that cause and sustain transformation." (PMID 38580649, 2024). "Aberrant overexpression of UHRF1 is observed in a number of types of cancer, and the overexpression of UHRF1 suppresses the transcription of TSGs through DNMT1-mediated DNA methylation." (PMID 39267107, 2024). "DNMT1, DNMT3b, HDAC1, and HDAC3 have been reported to be highly expressed in choriocarcinoma cancer stem-like cells." (PMID 38988323, 2024). "The DNMT1 and DNMT3A or -3B family proteins are known targets for the inhibition of DNA hypermethylation in cancer cells." (PMID 38866895, 2024). "DNMT1 and DNMT2 are positively correlated with most cancers, while DNMT3A and DNMT3B are inversely correlated with most cancers." (PMID 38166842, 2024). "Studies have shown that an overexpression of DNMT1 and DNMT3A, enzymes responsible for methylation, correlates with lower ERα levels and poor prognosis in cancer." (PMID 39796024, 2024). "Here the authors show that, beyond activating DNMT1, UHRF1 has crucial regulatory functions in cancer cells." (PMID 38580649, 2024). "Recent studies have shown that SFN influences certain cancers through epigenetic mechanisms such as microRNA (miRNA) modulation, histone deacetylase (HDAC) inhibition, and reducing the expression of DNA methyltransferase 1 (DNMT1)." (PMID 39148948, 2024). "Another DNMT1-selective inhibitor (GSK3685032) was developed with transcriptional activation and cancer cell growth inhibition properties." (PMID 39595939, 2024). "Reduction of DNMT1 promotes PCa metastasis through the induction of EMT, cancer stem cell phenotype, or neuroendocrine differentiation." (PMID 36755811, 2023). "When the demethylation reagent 5-AzadC is applied, the hypermethylation regulation of MEG3 by DNMT1 is significantly inhibited, and uninhibited MEG3 exerts its inhibitory effect on cancer through the inhibition of Notch1 signaling pathway." (PMID 37901333, 2023). "The relationship between the expression of four methyltransferase genes (DNMT1, (DNMT2, DNMT3A, DNMT3B) and SNAI2 in pan-cancer was investigated further." (PMID 37251370, 2023). "piR-651 increased DNMT1 enzyme activity, and further studies found that DNMT1 bound to the promoter region of the tumor suppressor gene PTEN, resulting in decreased expression and promoting cancer progression." (PMID 37901333, 2023).
cancer (continued). "Resveratrol decreases DNMT1 and DNMT3B expression levels and modulates the aberrant expression profiles of microRNAs (miRNAs) in cancer cell lines and tumour tissues." (PMID 37111085, 2023). "Our analysis revealed a significant correlation (p < 0.05 between DNMT1 and ADORA2A, IL10RB, and CTLA-4 in certain cancers." (PMID 37628671, 2023). "Mounting evidence has indicated that miR-148/-152 family members target the DNMT1 3′UTR in the development and progression of human cancer." (PMID 36959680, 2023). "Studies have also shown that PIWIL1 induces hypermethylation of PTEN by increasing the expression of DNMT1 and inhibiting the tumor suppressor PTEN to promote cancer progression." (PMID 38031146, 2023). "Targeting DNA methyltransferase 1 (DNMT1) has immunomodulatory and anti-neoplastic activity, especially when paired with cancer immunotherapies." (PMID 37055433, 2023). "With the knockdown of the upstream inhibitory target DNMT1, the highly expressed MEG3 shows high potential for cancer inhibition, including inhibiting cancer cell proliferation and promoting apoptosis, and inhibiting EMT through Notch1 signaling pathway." (PMID 37901333, 2023). "Further studies showed that overexpression of miR‐29b‐1‐5p inhibited DNMTs (DNMT1, DNMT3A, and DNMT3B) and promoted the expression of some cancer suppressor factors." (PMID 37901333, 2023). "MLL4 expression is positively correlated with levels of DNMT1 and DNMT3A in most TCGA human cancer types and across human cancer cell lines." (PMID 36323669, 2022). "This study was designed to compare the effects of locally sourced BSO with those of pure TQ on the expression of the epigenetic complex UHRF1/DNMT1/HDAC1 and the related events in several cancer cells." (PMID 35566130, 2022). "It is known that increased DNMT1 and DNMT3B expression play a significant role in the development and progression of several cancers, increasing the promotor methylation of several tumor suppressor genes." (PMID 36499741, 2022). "We noted that EVA1B presented negative interactions with four major DNA methyltransferases containing DNMT1, DNMT2, DNMT3A, and DNMT3B in most cancer types." (PMID 35250982, 2022). "The reduced sensitivity to OXPHOS inhibition of cancer cells upon NNMT overexpression and DNMT1 knockdown was also reflected by attenuated ATF4 upregulation and p‐S6 downregulation when treated with OXPHOS inhibitors (Gboxin, Oligomycin A, and Berberine)." (PMID 36382559, 2022). "DNA (-cytosine-5)-methyltransferase 1 (DNMT1) has been reported for silencing TNFα-RAPK1 and RIPK3-mediated necroptosis in cancer cell lines through hypermethylation." (PMID 36349193, 2022). "For instance, in esophageal cancer (EC), lncRNA ADAMTS9-AS2 was reported to recruit DNMT1/3 to CDH3 promoter, inhibiting the cancer cell proliferation, invasion, and migration." (PMID 35292092, 2022). "In bladder cancer, CpG site methylation of the PTEN promoter dependent on DNMT1 contributes to the poor expression of PTEN, which is regarded as a suppressor of cancers." (PMID 35838271, 2022). "Since both DNMT1 and HDAC1 are well-documented partners of the epigenetic reader UHRF1 in cancer cells, we studied the 24 h effect of BSO on the mRNA expression of the trimeric complex UHRF1, DNMT1 and HDAC1 in cancer cells." (PMID 35566130, 2022). "Currently, several histone modification regulators, including DOT1L, DNMT1, EZH2, and KDM5B, have been reported to play a role in the TGFβ-stimulated ZEB2 transcriptional upregulation of many cancers." (PMID 35606881, 2022).